IL1B (interleukin 1 beta)
Diseases named in the same sentence as IL1B in open-access papers (continued):
Sharing a sentence is not in itself a finding about the gene and the disease.
periodontitis (continued). "Not surprisingly, the variants of IL1B and IL6 genes have been associated with other chronic inflammatory conditions such as periodontitis, cancer, osteoporosis, type 2 diabetes and diabetic nephropathy." (PMID 35964023, 2022). "Plumbagin inhibits chronic periodontitis by downregulating the TNF-α, IL-1β, and IL-6 expressions." (PMID 36589679, 2022). "IL-1β level in PISF in patients with implants reached 23.73 ± 27.07 pg/mL and was significantly lower than in GCF in patients with mild (p = 0.029), moderate (p = 0.0005), and severe (p = 0.000014) periodontitis." (PMID 33726736, 2021). "Salivary IL-1β and TNF-α were also assessed as pro-inflammatory molecules related to periodontitis." (PMID 34950607, 2021). "According to our findings, while IL-1β and IL-6 levels had a tendency to be higher in the periodontitis group, the difference with the healthy group was not significant." (PMID 35048079, 2021). "In addition, according to a recent study, it was found that the expression of IL-1β and NLRP3 inflammasome was higher in gingival tissue of periodontitis than in normal tissue." (PMID 34356813, 2021). "Periodontitis increased mRNA expression of TNF-α and IL-1β in the kidneys." (PMID 34445604, 2021). "IL-1β induction was also lower in the presence of OBMC-derived supernatants from periodontitis patients, but with no statistical differences." (PMID 33672708, 2021). "Mechanistic investigation revealed that the caspase-4/GSDMD/IL-1β non-canonical pyroptosis pathway was the major contributor to the pathogenesis of periodontitis." (PMID 33869229, 2021). "Thus, this study aimed to investigate the IL-1β, CXCL8, and TNF-α levels in GCF in patients with different degrees of periodontitis and PISF in patients with healthy implants." (PMID 33726736, 2021). "A recent systematic review reported that the interleukin-1 beta, interleukin-6, macrophage inflammatory protein-1 alpha, and matrix metalloproteinase-8 (MMP-8) levels are potential salivary biomarkers for the diagnosis of periodontitis." (PMID 34415974, 2021). "As found in the present study, in T2DM patients with periodontitis, statins treatment reduced pro-inflammatory factors IFN-γ, IL-1β, IL-2, IL-6, IL-7, IL-21 and TNF-α levels in GCF, and enhanced anti-inflammatory factors IL-4 and IL-5 levels through the anti-inflammation and anti-oxidation effects." (PMID 33417619, 2021). "Moreover, the proinflammatory cytokines, such as IL-1β, IL-6, and TNF-α, have been used as biomarkers to diagnose periodontitis and peri-implantitis." (PMID 34931168, 2021). "Since supernatants obtained from OBMCs of periodontitis patients contain significant levels of pro-inflammatory cytokines such as TNF-α, IL-6 and IL-1β, these cytokines may be inhibitory for the induction of IFN-γ." (PMID 33672708, 2021). "Overall, IL-1β release in PDLSC pyroptosis both damaged the differentiation capability of circumjacent PDLSCs and promoted the formation of osteoclasts, which jointly aggravated the process of periodontitis." (PMID 33869229, 2021). "Further investigation also confirmed the anti‐inflammatory effects of BBR in periodontitis, as it has been shown that following treatment with BBR, the expression levels of pro‐inflammatory cytokines including TNF‐α, IL‐1β, and RANKL markedly downregulated in rat with periodontitis." (PMID 34719112, 2021). "In patients with periodontitis, lower levels of pro-inflammatory factors IFN-γ, IL-1β, IL-2, IL-6, IL-7, IL-21, TNF-αand higher levels of anti-inflammatory factors IL-4 and IL-5 in gingival crevicular fluid in the Sp group were identified than those in the Dp group." (PMID 33417619, 2021). "Therefore, we selected these four marker candidates (IL-1β, MMP-8, ICTP, and Pg) and evaluated their efficiency for diagnosing gingivitis and periodontitis." (PMID 34001101, 2021).
periodontitis (continued). "Unlike in GI tract and skin, the differentiation of Th17 cells in the oral cavity is independent of IL-1β, but IL-1β still appears critically positioned in the etiology of periodontitis, especially in immunomodulation and bone resorption." (PMID 34557201, 2021). "IL-1β activates generation of matrix metalloproteinase (MMP)-9 in periodontitis and promotes the expression of the receptor activator of nuclear factor kappa-B ligand (RANKL), contributing to osteoclastogenesis in periodontitis." (PMID 32328131, 2020). "In our study, serum IL-1β levels progressively increased from healthy (Group 1) to stage III periodontitis (Group 4) and salivary IL-1β levels were higher in gingivitis group than in stage I periodontitis group." (PMID 32997091, 2020). "Finally, the AUC was 0.88 (95% CI: 0.772–0.998, p < 0.001) for IL-1β, which suggests that CGF amounts of IL-1β ≥ 115.26 pg in moderate sites identify the presence of highly progressive periodontitis, with a sensitivity of 0.94 and a specificity of 0.70." (PMID 33218047, 2020). "Similarly, we found the staining of IL-1β, ASC, and Caspase-1 was also significantly stronger in periodontitis group." (PMID 32903638, 2020). "Since IL-1β and TNF-α are two of the most important inflammatory factors in the progress of periodontitis, we characterized the effects of different dynamic cyclic stress on these protein expressions in LPS-induced inflammatory hPDLCs to extend our observations at the mRNA level." (PMID 31907038, 2020). "Furthermore, recent proteomic investigation also confirmed that MMP8 along with other cytokines (interleukin-1b–IL-1b, RANK/RANKL/OPG) were overexpressed in periodontitis." (PMID 32646009, 2020). "Decreases in IL-1β and TNF-α levels were found to reduce periodontitis progression." (PMID 33343358, 2020). "Notably, most of activators of this pathway such as bacterial lipopolysaccharides, prostaglandin E2, IL-1β and TNF-α are abundantly present and active in the process of periodontitis." (PMID 32426538, 2020). "SRP was effective in reducing IL-1β total amounts in both moderate and deep sites (p < 0.001 for Grade C and p < 0.05 for Grade B, respectively) and TNF-α levels in deep sites (p < 0.05) of both periodontitis groups." (PMID 33218047, 2020). "Studies have suggested that specific cytokines (elastase, interleukin -IL-1, IL-2, IL-6, IL-13, IFN-γ, TNF-α) were increased while others are decreased (IL-1β, IL-18) in either GCF or serum of SLE subjects, and similar alterations were observed in periodontitis patients." (PMID 31781106, 2019). "rs1143634 is a synonymous SNP (F105F) in exon 5 of IL-1β whose function is not completely elucidated; yet, it was found to be associated with several diseases including HIV-1 and periodontitis." (PMID 30728751, 2019). "mRNA expression of inflammatory cytokines IL-1β, IL-6, TNF-α and the RANKL/OPG mRNA ratio were increased in periodontitis patients compared with gingival samples of healthy controls (p < 0.05), matching the clinical diagnosis of periodontitis." (PMID 31848404, 2019). "The difference (delta of exposed vs unexposed) between the healthy and periodontitis group was not statistically significant for IL-1β (p = 0.18)." (PMID 31164964, 2019). "It is already known that the NLRP3 inflammasome and secretion of IL-1β are crucial for the development of PD, because in the absence of NRLP3 or IL-1β, there is no periodontitis induced by P. gingivalis in mouse models." (PMID 31341421, 2019). "Manifesting high levels of cytokines, such as IL-1β, IL-6, and TNF-α, periodontitis has an immunologic profile similar to that of RA and both diseases are associated with elevated concentrations of matrix metalloproteinases (MMPs) and low concentrations of tissue inhibitors of MMP (TIMPs)." (PMID 30211216, 2018).
periodontitis (continued). "TNF-α was not detectable in our minipig model of periodontitis, but the ELISA demonstrated that local icariin significantly decreased IL-1β expression, which indicates that icariin regulated inflammatory and immune reactions in periodontitis." (PMID 29895944, 2018). "Experimental models demonstrate that the development of periodontitis in diabetic rats involves a high expression of proinflammatory cytokines (TNF-α, IL-1β, IL-6) and destructive tissue factors as advanced glycation end products (AGEs) without significant changes in commensal oral microbiota." (PMID 30356347, 2018). "IL‐1β and TNF‐α are proinflammatory cytokines that are involved in the initiation and progression of chronic inflammation, and they are critical mediators in the progression of periodontitis." (PMID 29744190, 2017). "In addition, periodontal ligament cells secrete IL-10, which can be suppressed by IL-1β and it has been hypothesized that periodontal ligament cells can function as accessory immunoinflammatory cells amplifying the inflammatory process in periodontitis, thereby contributing to periodontal breakdown." (PMID 29075409, 2017). "The purpose of this study was to compare IL-1β and IL-12 gene expression in the gingival tissue of smokers and non-smokers either with healthy periodontium or with chronic periodontitis." (PMID 29299075, 2017). "When we compared this value between two groups, regardless of smoking, we found that the amount of IL-1β was significantly higher in periodontitis patients (p=0.027) than healthy groups." (PMID 29299075, 2017). "Nevertheless, analysis of for example periodontitis induced by ligatures (either previously incubated with P. gingivalis or not) or oral gavage application of P. gingivalis strain ATCC 33277, revealed elevated serum levels of IL-1β and IL-6." (PMID 28589098, 2017). "This study suggests that smoking cigarettes in patients with periodontitis significantly reduces IL-1β gene expression in comparison to nonsmoking patients." (PMID 29299075, 2017). "This issue (increased values of IL-1β) is even observed in non-diseased sites with low probing depth in patients with severe periodontitis forms which led to considering patients and genotype factors that involved in host’s response to bacterial coping." (PMID 29299075, 2017). "IL-1β gene expression increases in gingival tissue of non-smoker-chronic periodontitis patients due to inflammatory processes but smoking reduces the expression of this cytokine in diseased periodontal tissues." (PMID 29299075, 2017). "IL-1β gene expression in gingival tissue of non-smoker group with chronic periodontitis was significantly higher than non-smoker-healthy group (p=0.011)." (PMID 29299075, 2017). "Smoker-chronic periodontitis group showed lower IL-1β gene expression than non-smoker-chronic periodontitis group (p=0.003)." (PMID 29299075, 2017). "The level of IL-1β gene expression among nonsmoker periodontitis patients compared to nonsmoker healthy individuals was significantly higher." (PMID 29299075, 2017). "Therefore, we readily understand the high proportions of IL-1β and TNF-α and a more aggressive immune reaction in peri-implantitis compared with periodontitis." (PMID 28864780, 2017). "Figs. (1 and 2) show the values of IL-1β and IL-12 in individuals with healthy periodontal tissues and in smoker and nonsmoker patients with periodontitis." (PMID 29299075, 2017). "Cytokines like IL-1α, IL-1β, IL-6, IL-8, and TNF-α have been documented to be involved in immune activation, increased cytotoxic activity, and cytokine-mediated osteoclastic bone resorption in aggressive forms of periodontitis." (PMID 27642305, 2016). "In addition, there was a positive correlation between NLRP3 and IL-1β expression levels in these tissues, confirming the involvement of NLRP3 inflammasome in the pathogenesis of periodontitis." (PMID 27632566, 2016). "The result showed that IL-1β and TNF-α were upregulated in LPS-induced periodontitis rats." (PMID 27216891, 2016).
periodontitis (continued). "IL-1β levels in gingival tissues and GCF correlates with the inflammatory status of periodontal disease, indicating the fundamental role of IL-1β in the pathogenesis of periodontitis." (PMID 27632566, 2016). "To study this, we stimulated human polymorphonuclear leukocytes (PMNs) and peripheral blood mononuclear cells (PBMCs) with dental calculus collected from periodontitis patients, and measured IL-1β secretion by ELISA." (PMID 27632566, 2016). "The results of qPCR analysis of liver tissue indicated that liver IL1β expression was significantly higher in GFPWT:WT chimeras with periodontitis vs. no periodontitis at 18 weeks (p <0.05)." (PMID 26317345, 2015). "Salivary IL-1β is significantly higher in patients with severe periodontitis than in healthy controls; however, IL-1β does not differ between patients with mild periodontitis and healthy controls." (PMID 25884025, 2015). "Pro-inflammatory interleukin-1β (IL-1β) and tumor necrosis factor-α (TNF-α) play a prominent role in periodontal inflammation and are elevated in gingival crevicular fluid (GCF) and in gingival tissue in periodontitis." (PMID 26241961, 2015). "In a study of 12 patients with moderate to advanced periodontitis, no statistically significant reduction in the total levels of IL-1β and -10 following nonsurgical therapy was observed." (PMID 24944641, 2014). "On the other hand, plasma levels of all the interleukins studied (IL-1β, IL-6, IL-11) were not significantly different between study groups (chronic periodontitis, generalized aggressive periodontitis, gingivitis, healthy subjects)." (PMID 25299619, 2014). "Thus, IL-1β, TNF-α, and PGE2 will all activate osteoclast activity, MMP secretion, and alveolar bone resorption in chronic periodontitis." (PMID 24944840, 2014). "Although both salivary MIP-1α and IL-1β were elevated in subjects with periodontitis in this study, the level of MIP-1α is considered to be a more sensitive biomarker for periodontitis as levels of salivary MIP-1α were increased 50-fold in contrast to the mere 5-fold elevation of IL-1β." (PMID 24944840, 2014). "The aftermath of inflammatory progression of periodontitis systemically leads to production of mediators in the vicinity such as C-reactive protein (CRP), interleukins-1beta (IL-1β), tumor necrosis factor-alpha (TNF-α) and interleukin 6 (IL-6) i.e Proinflammatory cytokines." (PMID 24198887, 2013). "Considering the role of inflammatory mediators in periodontitis, the aim of the present study was to compare the effects of FMD with the quadrant-wise scaling and root planing (Q-SRP) on serum levels of IL-17 and IL-1β in patients with moderate-to-severe chronic periodontitis." (PMID 25512752, 2013). "Other important candidate factors that may modulate periodontitis, are pro-inflammatory cytokines [such as tumor necrosis factor-a (TNF-a), interleukin (IL)-1β] known to be up-regulated early in the course of periodontitis." (PMID 21092263, 2010). "gingivalis successfully induced periodontitis in mice and led to EndoMT in the hippocampus, characterized by downregulation of ZO-1 and Claudin-5 and upregulation of α-SMA, along with inflammatory activation evidenced by elevated levels of iNOS, IL-1β mRNA, and IL-6 mRNA." (PMID 41908490, 2026). "Interestingly, patients suffering from severe periodontitis showed high IL-1β regardless of pocket depth, even after treatment." (PMID 41440367, 2025). "Furthermore, a positive association has been established between USP5 overexpression and enhanced production of pro‐inflammatory cytokines, including TNF‐α, IL‐6 and IL‐1β in PDLSCs, suggesting that USP5 triggered inflammation and consequently aggravated periodontitis." (PMID 39626954, 2025). "Its ability to down-regulate cytokines such as IL-1β, TNF-α, and IL-6, its interaction with IL-17 signaling, and its role in controlling osteoclast differentiation and alveolar bone resorption highlight its broader relevance in the pathogenesis of periodontitis." (PMID 41289041, 2025).
periodontitis (continued). "(2015) reported that, both in patients with chronic periodontitis and T2DM, as well as human gingival epithelial cells (HGEC) stimulated with lipopolysaccharide (LPS) and high concentrations of glucose, showed a significant increase in the expression of the NLRP3 inflammasome and IL-1β." (PMID 40406515, 2025). "Interventional studies have shown that in patients with periodontitis, non-surgical periodontal treatment significantly reduces IL-1β levels, suggesting that successful therapy may prevent disease progression at least partially by suppressing IL-1β activity." (PMID 40572711, 2025). "The ability of IL-10 to modulate key pro-inflammatory cytokines such as IL-1β, TNF-α, and IL-6, along with its interplay with IL-17 signaling and its regulatory effects on osteoclast differentiation and ABL, points to its multifaceted role in the pathophysiology of periodontitis." (PMID 41289041, 2025). "On day 7 after periodontitis induction and treatment administration, blood was drawn from the inferior vena cava, totaling 10 mL, to obtain blood serum for determining the levels of proinflammatory cytokines TNF-α, IL-1β, and anti-inflammatory cytokines IL-10, IL-13 through ELISA examination." (PMID 39539670, 2024). "Moreover, a bi-directional relationship is suggested by several authors because of the increased production of pro-inflammatory cytokines such as IL1B, IL4, IL6, IL10, CBL, and RELA, which are often present in the periodontitis development and CRC carcinogenesis." (PMID 39517401, 2024). "However, when comparing periodontitis groups to healthy controls and gingivitis groups, IL-1B levels were not significantly different." (PMID 38086426, 2024). "While periodontitis might contribute to increased IL-8 production, existing studies suggest that specific interleukin SNPs (like IL-1B and IL-17) are not significant risk factors for both T1DM and periodontitis development." (PMID 38397350, 2024). "However, after periodontal therapy, smoking periodontitis patients showed significantly higher IL-1β levels in their GCF than nonsmoking patients." (PMID 36726081, 2023). "However, for IL-1β in serum, after omitting one study, the smoking patients with periodontitis showed significantly lower values than nonsmoking patients." (PMID 36726081, 2023). "However, after periodontal therapy, smoking periodontitis patients showed significantly higher GCF IL-1β levels than nonsmoking periodontitis patients." (PMID 36726081, 2023). "In this double-blind study with a placebo control, the effectiveness of resveratrol as a supplementary treatment for clinical indicators (PD, CAL, PI, and BI) and salivary inflammatory indicators (IL-8 and IL-1β) was investigated in chronic periodontitis patients without any systemic disease." (PMID 36973728, 2023). "The structure of the IL1β protein and its interaction with the RNA around the alternate or reference SNPs at IL6-1363 might provide information as to how this form of epistasis operates in periodontitis; Supplement, Section S4." (PMID 37762554, 2023). "In addition, our ligature-induced model confirmed the distinguished bone resorption and the pro-inflammatory gene expression of IL-1β, TNF-α, CCL-2, Nos2, IL-17 and IL-6, which were highly enhanced during the progress of the early acute phase of new periodontitis." (PMID 38069063, 2023). "Moreover, this meta-analysis found that periodontitis patients who smoked showed significantly higher IL-1β values in GCF than nonsmoking periodontitis patients after periodontal therapy." (PMID 36726081, 2023). "Unlike IL-6, IL-1β does not present similar levels in peri-implantitis and in periodontitis." (PMID 37232785, 2023). "Interestingly, results showed an up-regulation of colony-stimulating factor-1 (CSF-1), S100A8/A9, S100A12, interleukin (IL)-1β, matrix metalloproteinase (MMP)-8, and hepatocyte growth factor (HGF), in patients with periodontitis with a statistical significance of p<0.001." (PMID 37224160, 2023).